LIF (LIF interleukin 6 family cytokine)
Diseases named in the same sentence as LIF in open-access papers (continued):
Sharing a sentence is not in itself a finding about the gene and the disease.
cancer (continued). "Targeting LIF has been actively investigated as a novel strategy for cancer therapy." (PMID 35992780, 2022). "Recent studies on LIF in cancer have further demonstrated LIF-LIFR mediated YES activation." (PMID 34395259, 2021). "There has been a significant focus throughout the years on STAT3 being the causal driver of LIF mediated effects in cancer, and not without cause—our primary understanding of LIF is derived through its effects on mESCs via STAT3." (PMID 34395259, 2021). "In this article, we provide an overview of LIF involvement in key cancer-promoting processes." (PMID 33630157, 2021). "Recent studies suggested LIF-LIFR axis as a promising therapeutic target for cancer therapy." (PMID 34716410, 2021). "Indeed, LIF concentration correlates with the density of polarised collagen fibres in Sirius Red staining of xenograft model samples, as well as cancer cells invasiveness and poor clinical outcome." (PMID 33630157, 2021). "Generally speaking, cancer stem cell maintenance by LIF and LIFR seem to follow a similar trend as that seen in mESCs: LIF signaling leads to the activation of STAT3, which increases the stem cell like properties in solid tumors through transcriptional regulators." (PMID 34395259, 2021). "LIF and LIFRβ expression are linked to a variety of human cancers, many of which are associated with both negative and positive prognostic outcomes." (PMID 34395259, 2021). "Recent studies suggested LIF/LIFR axis as a promising clinical target for cancer therapy." (PMID 34716410, 2021). "They further demonstrate that this engineered LIFR exhibits improved affinity relative to the wild-type receptor, leading to better disruption of LIF signaling in cancer cells, and highlighting promise of such ligand traps as therapeutic strategy for cancer treatment." (PMID 33846527, 2021). "LIF also displays several functions on development and progression of cancers." (PMID 32651426, 2020). "Despite presence of other fibroblast activator molecules in the TME, considering TGFβ and LIF signaling pathways seems to be sufficient to model the interactions among fibroblasts and cancer cells due to their consecutive roles in the promotion of fibroblasts activation." (PMID 32384110, 2020). "Leukemia inhibitory factor (LIF) has been studied in different cancers, while the role of LIF in OSCC remains unclear." (PMID 31973037, 2020). "LIF regulated cancer cell motilities through outside-in signaling." (PMID 31973037, 2020). "All this evidence indicates that LIF:LIFR axis might be an attractive target for cancer immunotherapy." (PMID 32651426, 2020). "We demonstrated a novel mechanism (INHBA regulation) by which LIF influences cancer progression." (PMID 31973037, 2020). "LIF was identified as an essential factor under the control of a cancer-specific SE." (PMID 32382065, 2020). "Furthermore, univariate analysis was used to investigate the relationships of LIF expression and cancer characteristics with patients’ overall survival." (PMID 31973037, 2020). "Moreover, induction of IL‐6 and LIF by TGFβ has been reported in different types of fibroblasts including CAFs in other cancers." (PMID 31609088, 2019). "Further studies are needed to determine whether LIF and IL-6 counter-regulate development of T cell lineages in the microenvironment of cancers." (PMID 31296870, 2019). "Moreover, results of time-course experiments on cells treated with recombinant human LIF showed that in WT cancer cells, LIFR desensitization occurred at 30 min and is sustained up to 2 h post-LIF treatment." (PMID 30504771, 2018). "In our cell model, LIF/LIFR-rich cancer cells (cLIF) expressed lower levels of phosphorylated YAP1 as well as total YAP1 protein, leading to the hypothesis that LIF regulates LIFR–YAP1 signaling to promote NPC invasive phenotypes." (PMID 30504771, 2018). "In immunohistochemical analysis, LIF was detected in cancer stromal fibroblasts." (PMID 29444110, 2018).
cancer (continued). "Here, we aimed to investigate whether LIF modulates cancer adhesion to facilitate metastatic dissemination." (PMID 30504771, 2018). "WT and LIF+/− cancer cells expressed medium to high levels of YAP1." (PMID 30504771, 2018). "From the therapeutic point of view, treating LIF-high NPC cells with AZD0530 may potentially prevent cancer dissemination by inactivating YAP1-SRC-focal adhesion signaling." (PMID 30504771, 2018). "Results from studies using conditioned medium to understand the mechanism of myotube atrophy have shown involvement of a number of cancer cell secreted factors (TNFα, IL-6, LIF), and target cell signaling proteins and transcription factors such as C/EBPβ, C/EBPδ, STAT3, P38." (PMID 28993738, 2017). "Thus, myotubes incubated with C26 CM were exposed to higher levels of LIF for a longer time compared to myotubes incubated with Transwell inserts containing C26 cancer cells." (PMID 28993738, 2017). "Indeed, recent studies including ours show that LIF overexpression enhances resistance towards cancer therapy." (PMID 26716902, 2016). "Overexpression of LIF promoted morphological changes of cells from epithelial-like to mesenchymal-like, increased the expression of mesenchymal markers and decreased an epithelial marker in human cancer cells." (PMID 26716902, 2016). "In turn, LIF overexpression clearly increases the migration and invasion abilities of cancer cells." (PMID 26716902, 2016). "LIF is a multifunctional cytokine with a complex role in cancer." (PMID 26229239, 2015). "Leukemia inhibitory factor (LIF), a multi-functional cytokine, has a complex role in cancer." (PMID 25726527, 2015). "The nature of the functional effect of LIF in different cancer cell types are dependent upon the signal transduction pathways that may be activated downstream of the receptor." (PMID 26296968, 2015). "LIF plays an important and complex role in cancer depending upon the types of the cancer." (PMID 25726527, 2015). "Interestingly, abrogation of the proinvasive phenotype was observed with carcinoma-, LIF- and TGFβ-activated fibroblasts even after removal of the two inhibitors." (PMID 26667266, 2015). "Having shown that restriction of the DNMTs catalytic activities inhibits both the establishment and the maintenance of the proinvasive phenotype of carcinoma- and LIF-activated fibroblast, we first investigated the molecular mechanisms underlying the DNMT-dependent proinvasive fibroblast activation." (PMID 26667266, 2015). "Therefore, we conclude that in human carcinomas from different origins, LIF induces a sustained proinvasive activation of CAF through an epigenetic-dependent loss of SHP-1 phosphatase." (PMID 26667266, 2015). "LIF could inhibit the differentiation and promote proliferation in some cancers and cancer cell lines, and has been suggested to contribute to the progression of malignancies, including rhabdomyosarcoma, choriocarcinoma and melanoma." (PMID 24553191, 2014). "Levels of HGF and LIF were significantly higher in patients with pancreatic malignancy." (PMID 23672538, 2013). "In addition, lung preneoplastic and cancer cells have been shown to respond to LIF, a factor involved in cancer metastasis." (PMID 23667589, 2013). "Interestingly, hCG has been shown to transiently induce PROK1 in Ishikawa cells, a cancer cell line widely used as model for uterine epithelial cells, which was followed by increased LIF expression." (PMID 20422017, 2010). "Also, three cancer-associated proteins, GRO, LIF, TIMP-2 were also down-regulated, along with Leptin, an energy intake and expenditure regulator." (PMID 18282300, 2008). "However, in these cancer cells, LIF induces cell survival through signaling pathways that would not involve Stat3 activation." (PMID 17925034, 2007). "Intrinsic LIF signaling in cancer cells has been shown to promote cell growth and proliferation with increased energy demands, which may enhance the competition of cancer cells with host cells for nutrients." (PMID 38245529, 2024).
cancer (continued). "Importantly, HB-EGF treatment in cancer cells and CAFs mono-cultures shows that: LIF is strongly upregulated only by CAFs, indicating that these are the cells responsible for its production when in co-culture; CSF2 was upregulated by HB-EGF treatment both in cancer cells and in CAFs." (PMID 39262776, 2024). "Therefore, developing monoclonal antibodies (mAbs) targeting LIF to disrupt the downstream signaling pathway may be a potential strategy for cancer treatment." (PMID 39169307, 2024). "However, the effect and mechanism of LIF in cardiotoxicity in cancer progression and treatment remain unclear." (PMID 37103052, 2023). "Cancer-associated fibroblast-specific circ-FARP1 binds to CAV1 and inhibits its ubiquitination by ZNRF1 to enhance the secretion of LIF; in addition, circ-FARP1 sponges miR-660-3p to increase the expression of LIF, thereby promoting the stemness and GEM resistance of PDAC cells." (PMID 38044421, 2023). "Importantly, identifying LIF as expanding this niche cell type adds to our appreciation of stromal cells as active members of inflammatory pathology and supplements the roles LIF is already known to play in cancer." (PMID 37134077, 2023). "According to the circRNA target profiling and pathway enrichment analysis, the high‐confidence DECs could influence the expression of cancer stem cell‐associated core signature genes such as ALDH1A3, SOX9, CD109, LIF and BMPR1 via negative regulation of miRNAs." (PMID 35579852, 2022). "Although there have been nearly one thousand papers written that examine the actions and expression of LIF within various cancers, there have been limited clinical trials that have investigated a therapeutic aimed at altering LIF signaling for improving outcomes of cancer patients." (PMID 35204717, 2022). "LIF could partially control cancer cell immune tolerance by affecting monocytes." (PMID 35740622, 2022). "In addition, by using in vitro cancer cells and pharmacological approaches, we demonstrate that inhibition of LIF/LIFR signaling might have utility in the treatment of GC." (PMID 35847866, 2022). "In addition, key pathways that are induced by LIF have also been implicated as leading to survival of CSCs, even in cancers where LIF itself has not been directly implicated." (PMID 35204717, 2022). "LIF, a pleiotropic cytokine that belongs to the Interleukin (IL)-6 family, is overexpressed in a variety of solid tumours, including pancreas, stomach, liver, colon and breast, and promotes cancer cell proliferation, remodelling, invasiveness and epithelial-to-mesenchymal transition (EMT)." (PMID 36359879, 2022). "However, the role of LIF in cancer metabolic reprogramming is unclear." (PMID 35440095, 2022). "For instance, osteoblasts may secrete CXC chemokine ligand 12 (CXCL12), TGF-β, growth arrest-specific protein 6 (GAS6), osteoprotegerin (OPG), osteopontin (OPN), and leukemia inhibitory factor (LIF), to promote colonization and dormancy of disseminating cancer cells in bone marrow." (PMID 34685686, 2021). "Moreover, targeting miR-29c or LIF might provide new insight into developing potential therapeutic strategies for cancer cachexia." (PMID 34838029, 2021). "LIF has been shown to transmit biological information through a heterodimer receptor complex comprising LIF receptor and Interleukin 6 signal transducer in a variety of inflammatory processes, including acute phase reaction, hematopoiesis, bone metabolism, and cancer progression." (PMID 34781940, 2021). "However, we can speculate that IL‐6, IL‐11, and LIF secreted by PC may be responsible for some of them, as they have well‐known roles in cancer." (PMID 32767843, 2020). "Thus, LIF can be a potential target in preventing cancer metastasis and spread." (PMID 31973037, 2020).
cancer (continued). "In addition, our model describes the kinetic parameters of fibroblast signaling molecules (SLIT2 and CXCL12) with a polynomial which is dependent on cancer cell signaling factors (LIF and TGFβ); an attitude which is an innovative procedure in agent-based modeling structure." (PMID 32384110, 2020). "In addition, TGF-β and LIF signaling also play vital roles in the development of cancers." (PMID 32382065, 2020). "However, high LIF staining was also found in patients with advanced cancer stages." (PMID 31973037, 2020). "Consequently, WT and LIF+/− cancer-induced damage was relatively minor and could be repaired by HUVEC cells." (PMID 30504771, 2018). "Since cLIF cells exhibited a higher activity of SRC and consequently an enhanced EMT and invadopodia formation, we therefore investigated whether treatment of cancer cells with AZD0530 alters LIF-regulated expressions of p-YAP1 and focal adhesion molecules, which might affect SRC activity." (PMID 30504771, 2018). "To further characterize the mechanism by which intracellular LIF modulates breakdown of endothelial barriers, we utilized high-resolution time-lapse fluorescence microscopy, which provided spatial and temporal information on the interactions between cancer and HUVEC cells." (PMID 30504771, 2018). "Thus, targeting LIF has become a potential strategy in cancer therapy." (PMID 29899555, 2018). "Therefore, some degree of actomyosin contractility is essential for both cancer cells and stroma for efficient cell movement in the initial steps of the metastatic cascade, and some factors such as TGFβ and LIF can stimulate contractility both in cancer cells and in fibroblasts." (PMID 27158478, 2016). "The role of LIF in cancer and its underlying mechanisms are not well-understood with limited studies suggesting that LIF may play a role in tumorigenesis." (PMID 24553191, 2014). "We summarize the role of a breast cancer suppressor receptor (LIFR, CD118), part of the leukemia inhibitory factor (LIF, IL-6 family), which is inhibited in bone under low oxygen tensions and exhibits distinct influences in other cancers." (PMID 40977686, 2025). "The JAK-STAT3 pathway, predominantly activated by cytokines such as IL-6, IFNγ, LIF, and OSM, plays a central role in cancer cachexia pathogenesis." (PMID 40704145, 2025). "Leukemia inhibitory factor (LIF) is a critical cytokine involved in various biological processes, including stem cell self-renewal, inflammation, and cancer progression." (PMID 39989618, 2025). "We searched for other potential overlaps and found that CXCL2, LIF, UBE2C, KRT5, ICAM1, and CXCL8 were significantly upregulated in STIC lesions identified in patients with cancer compared with adjacent normal epithelium." (PMID 40689422, 2025). "PSCs secrete leukemia inhibitory factor (LIF), which regulates cancer cell differentiation and EMT, as well as influences chemotherapy resistance." (PMID 40136652, 2025). "Leukemia inhibitory factor (LIF) and its receptor (LIFR) play a major role in cancer stemness, progression, metastasis, and therapy resistance." (PMID 40804837, 2025). "Previous studies have also found that decreased LIF expression, driven by miR‐637 overexpression, inhibits STAT3 phosphorylation and cancer cell growth in HCC." (PMID 40416597, 2025). "A multi-omic screening then identifies leukemia inhibitory factor (LIF) and galectin-3 (Gal3) as the key cytokines released by these cancer cell types to trigger brain activation." (PMID 38467743, 2024). "Remarkable increases in intracellular LIF mRNA expression and LIF release in supernatants were observed in 3D tumorsphere culture derived from HNSCC cell lines and patient‐derived cancer cells (PDC) as compared to their corresponding monolayer culture." (PMID 39206755, 2024). "T cells in adipose tissue release leukemia inhibitory factor (LIF), a cytokine from the IL-6 family, which controls stem cell self-renewal, inflammatory response, and cancer progression." (PMID 39596205, 2024).
cancer (continued). "Therefore, we hypothesized that LIF could be a promising target for the treatment of cancer." (PMID 39169307, 2024). "CAFs assert their pivotal role within this vicious cycle, actively shaping an inflamed neoplastic niche where IL-6, IL-11, LIF, and CXCL5 orchestrate an inflammatory phenotype that fuels cancer progression." (PMID 39609411, 2024). "The LIF/STAT3/FGFR4 axis can serve as survival mechanism to promote the growth of neoplastic cells and development of cancer cells chemoresistance." (PMID 37945798, 2024). "CSF2/GM-CSF is produced both by cancer cells and CAFs when stimulated with HB-EGF, while LIF is specifically produced by CAFs." (PMID 39262776, 2024). "Beyond IL-6, other members of the IL-6 cytokine family, such as IL-11, leukemia inhibitory factor (LIF), and oncostatin M (OSM), also play critical roles in the interplay between inflammation and cancer." (PMID 39421736, 2024). "These approaches targeting LIF augmented the efficacy of chemotherapy to prolong survival of PDAC mouse models, primarily by modulating cancer cell differentiation and epithelial–mesenchymal transition status." (PMID 37174079, 2023). "These cells secrete LIF and IL6, which are required to sustain cancer cell line growth and survival." (PMID 36602390, 2023). "The most relevant of which is that the role of LIF/LIFR system has been tested in in vitro models and therefore the real anti-cancer potential of BAR502 in PDAC should be further investigated in clinically relevant settings." (PMID 36998446, 2023). "Network analysis identified a key role of mesothelial cells, which communicated with cancer cells by TNC and LIF, and distinct immune cells, including all subtypes of DCs, macrophages, and monocytes by ICAM1." (PMID 37649596, 2023). "Clinically, the activation of the LIF/LIFR axis is correlated with poor prognosis and resistance to anti-cancer therapies." (PMID 36925915, 2023). "IL-1α and LIF display cooperative effects in activating EMH and are both up-regulated in some human cancers." (PMID 37134077, 2023). "LIF and LIFR, members of the interleukin-6 (IL-6) cytokine family, constitute a poorly-defined pathway connecting inflammation to cancer." (PMID 36925915, 2023). "LIF-LIFR signaling is involved in cancer progression and its deregulation occurs in multiple cancers." (PMID 36925915, 2023). "These include TNF-α, interleukins (IL-6; IL-1β and IL-1α), interferon-gamma (IFN-γ), leukemia inhibitory factor (LIF), and the TGF-β superfamily have been shown to mediate cancer-induced muscle wasting." (PMID 38203683, 2023). "We showed that two members of the IL-6 family, LIF and OSM, induce JunB upregulation in microglia, a finding that was previously reported with respect to LIF-treated human carcinoma cells and to OSM-treated primary chondrocytes." (PMID 37894348, 2023). "The expression of gene LIF/LIFR is overexpressed in solid tumors, and plays an essential role in cancer metastasis, progression, and invasion." (PMID 36419120, 2022). "As a member in IL-6 family, leukemia inhibitory factor (LIF) has an crucial role in both embryonic stem (ES) cells and cancer development, which is necessary to maintain mouse ES cells in an undifferentiated condition via STAT3 activation." (PMID 35924148, 2022). "The lncAMPC/miR-637/LIF axis in PCa, HOTTIP/miR-637/LASP1 axis in CHOL, LOC646616/miR-637 axis in essential hypertension, exert oncogenic effects in cancer." (PMID 36175921, 2022). "LIF belongs to the interleukin-6 (IL-6) family of cytokines, promotes EMT, and is envisioned as a potential therapeutic target in many cancers." (PMID 35847866, 2022). "In addition to its physiological roles, the LIF/LIFR axis has been broadly discussed in the context of chronic inflammation, including chronic airway inflammation, cutaneous inflammation, neuroinflammation, and cancer-associated inflammation, mostly as an anti-inflammatory cytokine." (PMID 36329823, 2022).